YTHDF1 (YTH N6-methyladenosine RNA binding protein F1)
Diseases named in the same sentence as YTHDF1 in open-access papers (continued):
Sharing a sentence is not in itself a finding about the gene and the disease.
hypopharyngeal squamous cell carcinoma (4 papers, 2022 to 2025). "YTHDF1 is closely associated with iron metabolism in hypopharyngeal squamous cell carcinoma (HPSCC) patients." (PMID 40271153, 2025). "YTHDF1 was also associated with intratumoral iron and ferritin levels in hypopharyngeal squamous cell carcinoma (HPSCC) patients." (PMID 35186927, 2022). "When Ye and collaborators evaluated the correlation between the m6A modification and iron metabolism, they found that YTHDF1 regulates growth and iron metabolism in hypopharyngeal squamous cell carcinoma (HPSCC)." (PMID 35186927, 2022). "For example, YTHDF1 and YTHDC2 act as promoters of ferroptosis in hypopharyngeal squamous cell carcinoma (HPSCC) and lung adenocarcinoma (LUAD)." (PMID 40271153, 2025).
intrahepatic cholangiocarcinoma (4 papers, 2023 to 2026). A carcinoma that arises from the intrahepatic bile duct epithelium in any site of the intrahepatic biliary tree. "YTHDF1 was overexpressed in intrahepatic cholangiocarcinoma (ICC) and closely correlated to short survival of ICC patients, which was by increasing the translation of EGFR in a m6A-dependent manner." (PMID 36707507, 2023). "The N6-methyladenosine (m6A) reader YTH N6-methyladenosine RNA binding protein 1 (YTHDF1) plays a critical role in the tumorigenesis of intrahepatic cholangiocarcinoma (ICC), but its function in the tumor immune microenvironment remains unclear." (PMID 41969240, 2026). "YTHDF1 is upregulated in intrahepatic cholangiocarcinoma (ICC), and high levels of YTHDF1 could predict the poor prognosis of ICC patients." (PMID 36835633, 2023). "In addition, YTHDF1 and YTHDF2 facilitate the advancement of intrahepatic cholangiocarcinoma (ICC) through increasing EGFR mRNA translation and IFIT2 mRNA decay, respectively." (PMID 36999016, 2023).
lymph node metastasis (4 papers, 2021 to 2025). "Lymph node metastasis and the expression of PD‐1 and PD‐L1 are positively correlated with YTHDF1 levels." (PMID 39821576, 2025). "METTL3, YTHDC2, YTHDF1, and YTHDF2 had a remarkably high expression in PCa and CRPC with lymph node metastasis." (PMID 33403026, 2021). "The expression of METTL3, METTL14, WTAP, YTHDC2, YTHDF1, and YTHDF2 was remarkably higher in CRPC with lymph node metastasis than in CRPC with bone metastasis, whereas ALKBH5, FTO, and YTHDF3 were substantially decreased in CRPC with lymph node metastasis." (PMID 33403026, 2021).
neuroblastoma (4 papers, 2021 to 2024). Neuroblastoma (NB) is the most common solid, extracranial childhood tumor. "To explore the correlation between YTHDF1 gene polymorphisms and neuroblastoma susceptibility, we conducted the present eight-center case-control study in a Chinese population." (PMID 33758623, 2021). "Here, we attempted to evaluate the contributions of two polymorphisms (rs6011668 C>T and rs6090311 A>G) in the YTHDF1 gene to neuroblastoma susceptibility in 898 cases and 1734 controls that originated in China." (PMID 33758623, 2021). "In summary, our study indicates that YTHDF1 gene polymorphisms may weakly contribute to neuroblastoma susceptibility." (PMID 33758623, 2021). "Therefore, we conducted this eight-center case-control study to explore the association between SNPs in the YTHDF1 gene and neuroblastoma risk in Chinese children." (PMID 33758623, 2021). "In this eight-center case-control study, we assessed whether two SNPs (rs6011668 C>T and rs6090311 A>G) affect neuroblastoma susceptibility, which is located in the 5' region of YTHDF1, a vital region for regulating gene expression." (PMID 33758623, 2021). "Furthermore, mechanistic research should be carried out to expound on the underlying mechanisms by which YTHDF1 gene polymorphisms affect neuroblastoma susceptibility." (PMID 33758623, 2021). "In conclusion, our present results indicate that YTHDF1 polymorphisms (rs6090311 A>G) may affect neuroblastoma susceptibility in a low-penetrance and sex-dependent manner." (PMID 33758623, 2021). "However, no studies regarding the association between YTHDF1 gene polymorphisms and neuroblastoma susceptibility have been published." (PMID 33758623, 2021).
nonalcoholic fatty liver disease (4 papers, 2022 to 2026). "As regards metabolic diseases, METLL3 and the partner YTHDF1 promote the hepatic autophagic flux and the clearance of lipid droplets in nonalcoholic fatty liver disease." (PMID 36203590, 2022). "In addition, YTHDF1 together with METTL3 amplifies the function of Rubicon that inhibits autophagy by stabilizing Rubicon mRNA, and further blocks the clearance of lipid droplets (LDs) in mouse nonalcoholic fatty liver disease (NAFLD)." (PMID 36999016, 2023).
atherosclerosis (3 papers, 2022 to 2024). A disease characterized by the build-up of fatty material and calcium deposition in the arterial wall resulting in partial or complete occlusion of the arterial lumen. "UCHL5 modified by METTL14/YTHDF1 axis could facilitate the inflammation and vascular remodeling in atherosclerosis by activating the NLRP3 inflammasome." (PMID 37441706, 2023).
cardiac hypertrophy (3 papers, 2021 to 2024). "YTHDF1 and YTHDF3 coordinate the differentiation of cardiomyocytes from mouse embryonic stem cells, and YTHDF1 can suppress cardiac hypertrophy in an m6A-dependent manner." (PMID 38535111, 2024). "Subsequently, we further investigated the expression levels of YTHDF1/2/3 in the primary cardiomyocytes treated with ISO or PHE to induce myocardial hypertrophy in vitro, and in the mice with cardiac hypertrophy induced by TAC in vivo." (PMID 34266473, 2021). "Interestingly, YTHDF1 protein, but not mRNA expression level also significantly upregulated in the mice with cardiac hypertrophy induced by TAC." (PMID 34266473, 2021).
Cerebral ischemia (3 papers, 2022 to 2025). Restriction of arterial blood supply to the brain associated with insufficient oxygenation to support the metabolic requirements of the tissue. "YTHDF1 promoted RHBDF2 translation in an m6A-dependent manner in microglia after cerebral ischemia and reperfusion injury." (PMID 40898058, 2025).
diffuse large B-cell lymphoma (3 papers, 2021 to 2024). "For MSI, there were positive correlations with YTHDF1 expression in LUAD, LUSC, UCEC, BLCA, ESCA, and KIRC and negative correlations with in PRAD, COAD, and DLBC (lymphoid neoplasm diffuse large B-cell lymphoma)." (PMID 34026603, 2021).
ovarian serous cystadenocarcinoma (3 papers, 2021 to 2022). A malignant serous cystic epithelial neoplasm arising from the ovary. "The expression of YTHDF1, HNRNPC, IGF2BP1, VIRMA, and HNRNPA2B1 was significantly positively correlated with the ovarian serous cystadenocarcinoma (OV) tumor stem cell score (based on DNA methylation) (DNAss)." (PMID 34150845, 2021). "The results showed that YTHDF1 expression was related to different immune subtypes in BRCA, COAD, HNSC, KIRC, LGG (brain lower grade glioma), LUAD, LUSC, OV (ovarian serous cystadenocarcinoma), PRAD, SKCM (skin cutaneous melanoma), STAD, and UCEC." (PMID 34026603, 2021).
Stroke (3 papers, 2020 to 2025). Sudden impairment of blood flow to a part of the brain due to occlusion or rupture of an artery to the brain. "YTHDF1-regulated STAT5 translation mediates the protective role of ALKBH5 in stroke." (PMID 39519091, 2024). "The current study demonstrated that ischemia/reperfusion injury induced the upregulation of YTHDC2, in line with previously observed changes in YTHDF1 and YTHDF2 after stroke." (PMID 41154582, 2025). "Besides, the induction of YTHDC1 was observed after ischemia, which was consistent with the previous report that the abundance of YTHDF1 and YTHDF2 was also altered after stroke." (PMID 33188203, 2020).
adenomyosis (2 papers, 2020 to 2025). The growth of endometrial tissue inside the muscular wall of the uterine corpus. "As anticipated, we confirmed that YTHDF1 can interact with GPX4, and the enrichment of GPX4 was reduced in adenomyosis." (PMID 40911580, 2025).
autoimmune disease (2 papers, 2021 to 2025). A disorder resulting from loss of function or tissue destruction of an organ or multiple organs, arising from humoral or cellular immune responses of the individual to their own tissue constituents. "Therefore, functional regulation of YTHDF1 may serve to a promising therapeutic strategy for autoimmune diseases associated with high IFN signatures." (PMID 34324489, 2021). "Future studies focusing on how YTHDF1 regulates GC B cell selection and migration will be essential to further unravel the m6A-related mechanisms governing humoral immune dysregulation and may ultimately reveal novel therapeutic targets for autoimmune diseases." (PMID 41258073, 2025).
Cognitive impairment (2 papers, 2023 to 2025). Abnormal cognition is characterized by deficits in thinking, reasoning, or remembering. "The dysregulation of the m6A machinery, exemplified by deficiencies in YTH N6-methyladenosine RNA-binding protein F1 (YTHDF1) or the upregulation of circRNA regulating synaptic be exocytosis 2 (circRIMS2), exacerbates hippocampal synaptic defects and cognitive impairments in AD models." (PMID 40308894, 2025). "The brains of Mettl3−/− mice and Ythdf1−/− mice showed cognitive impairment similar to AD, in which the brains of Mettl3−/− mice showed microglia activation, and METTL3 overexpression mice prevented AβO-induced synaptic loss and cognitive impairment." (PMID 37255714, 2023).
diabetic kidney disease (2 papers, 2025). Progressive kidney disorder caused by vascular damage to the glomerular capillaries, in patients with diabetes mellitus. "Suoquan Yishen Formula promotes autophagy in diabetic nephropathy and improves renal cell senescence by inhibiting the YTHDF1-Rubicon axis." (PMID 41536046, 2025).
lymphoma (2 papers, 2021 to 2024). A malignant (clonal) proliferation of B- lymphocytes or T- lymphocytes which involves the lymph nodes, bone marrow and/or extranodal sites. "In contrast, YTHDF1 expression was significantly lower only in lymphoma." (PMID 34026603, 2021). "In clinical lymphoma samples, the expression of METTL3, YTHDF1, and TLR9 was highly correlated with immune cells infiltration." (PMID 38537697, 2024). "This analysis suggests that METTL3, YTHDF1, and TLR9 may have influence on lymphoma development and prognosis, via modulating immune microenvironments." (PMID 38537697, 2024).
osteoporosis (2 papers, 2021 to 2023). A condition of reduced bone mass, with decreased cortical thickness and a decrease in the number and size of the trabeculae of cancellous bone (but normal chemical composition), resulting in increased fracture incidence. "It was demonstrated that FTO was up-regulated during the osteogenic differentiation in human MSCs, by mediating m6A demethylation of osteoporosis biomarker in a YTHDF1-dependent manner." (PMID 37041485, 2023).
prostate (2 papers, 2021 to 2026). "Above all, our data support YTHDF1 as a critical downstream effector of EZH2 to promote prostate carcinogenesis." (PMID 41252201, 2026). "Analysis of YTHDF1 genomic alterations in urogenital cancers was explored with the cBioPortal website." (PMID 34026603, 2021). "Next, we used the UALCAN database to explore YTHDF1 expression in urogenital cancers with different clinical characteristics." (PMID 34026603, 2021). "Then, we used the TIMER database to further explore the correlation between YTHDF1 expression and different marker subsets of immune cells in six urogenital cancers." (PMID 34026603, 2021). "The relationships between YTHDF1 and marker genes of tumor-infiltrated immune cells in urogenital cancers were analyzed for confirmation." (PMID 34026603, 2021). "The results showed that YTHDF1 was strongly connected with marker genes of macrophages, Th1 cells, Th2 cells, Tfh cells, Treg cells, and Th17 cells in urogenital cancers." (PMID 34026603, 2021). "Next, we thoroughly analyze the connection between YTHDF1 expression and immune cell infiltration in six urogenital cancers." (PMID 34026603, 2021). "We used BLCA (n = 408) and PRAD (n = 497) as examples to demonstrate the potential immune function of YTHDF1 in urogenital cancers." (PMID 34026603, 2021). "The differential expression of YTHDF1 in urogenital cancers with different clinical characteristics was analyzed with the UALCAN database." (PMID 34026603, 2021). "YTHDF1 expression was positively related to immune cells in all urogenital cancers except TGCT." (PMID 34026603, 2021). "Moreover, we demonstrated that there were significant differences in YTHDF1 expression in different clinical subgroups of urogenital cancers, consistent with a previous study showing that YTHDF1 is expressed differently in KIRC at different stages." (PMID 34026603, 2021). "In addition, we explored the effect of YTHDF1 expression in urogenital cancers to verify the results in human cancers." (PMID 34026603, 2021). "In fact, YTHDF1 differential YTHDF1 expression existed in all urogenital cancers with diverse clinical characteristics, which indicated that YTHDF1 might play a role in the growth and progression of cancers." (PMID 34026603, 2021). "Furthermore, significant strong correlations between YTHDF1 expression and tumor immune-infiltrated cells (TILs) existed in human cancers, and marker genes of TILs were significantly related to YTHDF expression in urogenital cancers." (PMID 34026603, 2021).
Sjögren’s syndrome (2 papers, 2022 to 2024). "The mRNA level of YTHDF1 in PBMCs from patients with pSS was negatively correlated with the EULAR Sjögren’s syndrome disease activity index (ESSDAI) score." (PMID 36465909, 2022).
squamous cell carcinoma (2 papers, 2020 to 2022). A carcinoma arising from squamous epithelial cells. "The YTHDF1 mRNA expression was also significantly negatively associated with CD4, CD8, and FOXP3 mRNA expression in squamous cell carcinoma." (PMID 36479088, 2022). "In the squamous cell carcinoma group not receiving PD-1/PD-L1 inhibitor, the immunohistochemical expression of YTHDF1 was significantly negatively associated with CD4 and CD8 expression." (PMID 36479088, 2022). "In the squamous cell carcinoma group not receiving PD-1/PD-L1 inhibitor, the cutoff values of YTHDF1 and YTHDF2 were 45 and 40, respectively." (PMID 36479088, 2022).
testicular germ cell tumor (2 papers, 2020 to 2021). A germ cell tumor arising from the testis. "In the Kaplan-Meier plotter database, higher YTHDF1 expression was associated with poorer RFS in TGCT (testicular germ cell tumors) (n = 105, HR = 5.37, P = 0.011) and KIRP (n = 183, HR = 3.56, P = 0.027)." (PMID 34026603, 2021). "Some studies have shown that METTL3, ALKBH5, YTHDC1, YTHDF1, YTHDF2, and HNRNPC are the main m6A-related genes in type II testicular germ cell tumors." (PMID 32258108, 2020).
triple-negative breast carcinoma (2 papers, 2021 to 2024). An invasive breast carcinoma which is negative for expression of estrogen receptor (ER), progesterone receptor (PR), and human epidermal growth factor receptor 2 (HER2). "Six paired samples from two luminal B, two Her2 enriched, and two triple-negative breast cancer (TNBC) patients were used for IHC of METTL3, METTL14, FTO, YTHDF1, and YTHDF3." (PMID 34804948, 2021).
Wilms tumor (2 papers, 2021 to 2022). An embryonal neoplasm characterized by the presence of epithelial, mesenchymal, and blastema components. "We next determined the association between YTHDF1 gene polymorphisms and susceptibility to Wilms tumor in subgroups separated by age, sex, and clinical stages." (PMID 34151473, 2021). "We present, here, a hospital‐based case‐control study specifically designed to investigate the role of YTHDF1 genetic variants on Wilms tumor." (PMID 34151473, 2021). "The unconditional logistic regression was adopted to analyze the contributions of YTHDF1 gene single nucleotide polymorphisms (SNPs) to the risk of Wilms tumor." (PMID 34151473, 2021). "Our present work sheds some light on the potential role of YTHDF1 gene polymorphisms on Wilms tumor risk." (PMID 34151473, 2021). "The current work provided a collection of evidence regarding the role of YTHDF1 gene polymorphisms on risk of Wilms tumor." (PMID 34151473, 2021). "The objective of our case‐control study was to determine whether the YTHDF1 gene variants are associated with Wilms tumor risk." (PMID 34151473, 2021). "YTHDF1 is associated with the development of several kinds of cancers, yet whether common variants of the YTHDF1 gene influence Wilms tumor risk is unknown." (PMID 34151473, 2021). "YTHDF1 gene SNPs (rs6011668 C>T, rs6090311 A>G) could not contribute to the risk of Wilms tumor." (PMID 34151473, 2021). "However, whether YTHDF1 gene variants are related to the risk of Wilms tumor is not reported yet." (PMID 34151473, 2021).
astrocytoma (1 paper, 2020). "The expression of YTHDF1 was proportional to the brain tumor grade with the statistical significance of GBM vs. oligodendroglioma p = 0.0001, GBM vs. oligoastrocytoma p = 0.001, and GBM vs. astrocytoma p = 0.04." (PMID 33317545, 2020).
atrial fibrillation (1 paper, 2023). A disorder characterized by an electrocardiographic finding of a supraventricular arrhythmia characterized by the replacement of consistent P waves by rapid oscillations or fibrillatory waves that vary in size, shape and timing and are accompanied by an irregular ventricular response. "Five feature m6A regulatory genes, ZC3H13, YTHDF1, HNRNPA2B1, IGFBP2, and IGFBP3, were determined (p < 0.05) to establish a nomogram model that can predict the incidence of atrial fibrillation with the RF model." (PMID 37435047, 2023).
B-cell lymphoma (1 paper, 2025). "In line with this, EBNA2 transcripts interact with the YTHDF1-3 reader proteins in pull-down assays in latently infected B cell lymphoma cells." (PMID 39868828, 2025). "Knockdown of YTHDF2 via shRNA in latently infected B-cell lymphoma cells results in decreased EBNA2 transcript and protein levels, while knockdown of YTHDF1 and 3 results in their increased expression." (PMID 39868828, 2025).
bladder tumors (1 paper, 2021). "However, some m6A regulators, including METTL3, RBM15B, YTHDF1, YTHDF2, and IGFBP3, were significantly overexpressed in bladder tumors, and some m6A regulators, including METTL14, METTL16, ZC3H13, and YTHDF3, were markedly downregulated in bladder tumors." (PMID 35004726, 2021).
bone metastasis (1 paper, 2023). Transfer of a neoplasm from its primary site to bones. "Future studies would benefit from expanding sample sizes in a multicenter environment to establish a clearer relationship between the expression of METTL3, YTHDF1, ANLN and bone metastasis." (PMID 36923927, 2023).
brain cancer (1 paper, 2021). A primary or metastatic malignant neoplasm affecting the brain. "Higher expression of YTHDF1 showed worse survival in breast, soft tissue, bladder, lung and brain cancer." (PMID 34026603, 2021).
brain infarct (1 paper, 2025). "The forced expression of YTHDC1, a nuclear m6A reader protein, decreased brain infarct volume and promoted neuronal cell survival by facilitating Akt phosphorylation through degrading Pten mRNA, demonstrating an opposite role to YTHDF1." (PMID 40591025, 2025).
brain tumor (1 paper, 2020). "Following the identification of the potential involvement of YTHDF1 in brain tumor, we sought to assess the biological effect of YTHDF1 knockdown on GBM cells." (PMID 33317545, 2020).
Burkitt lymphoma (1 paper, 2024). A rare form of malignant mature B-cell non-Hodgkin lymphoma. "We transduced Akata (EBV+) Burkitt lymphoma cells with these constructs, establishing stable cell lines expressing either WT or mutant YTHDF1/3." (PMID 38236021, 2024).
cervical tumors (1 paper, 2025). "Research indicates that m6A regulators like METTL3, METTL14, and YTHDF1 are overexpressed in cervical tumors compared to normal tissues, with elevated METTL3 and YTHDF1 levels linked to poorer prognosis." (PMID 41029427, 2025).